INS (insulin)
Diseases named in the same sentence as INS in open-access papers (continued):
Sharing a sentence is not in itself a finding about the gene and the disease.
Hyperglycemia (continued). "However, in T2D, insulin fails to regulate glycogen synthesis and glucose production, leading to increased hepatic gluconeogenesis and hyperglycemia." (PMID 39376657, 2024). "Its therapeutic effect on hyperglycemia was evidenced by the reduction of blood glucose, serum insulin levels and HOMA-IR index while improving glucose tolerance and insulin sensitivity in skeletal muscle of db/db mice via activating insulin signaling PI3K/AKT pathway." (PMID 38799166, 2024). "We previously found that whereas selective AM hyperinsulinemia (accompanied by euglycemia) nearly completely suppressed circulating NEFA concentrations and enhanced PM HGU, selective AM hyperglycemia (with basal insulin) only reduced NEFA by 44% and did not enhance HGU." (PMID 39386695, 2024). "In some centres, individuals with hyperglycaemia but with HbA1c <48 mmol/mol (<6.5%) might not be started on insulin without the presence of symptoms." (PMID 38910151, 2024). "Second, we do not have information about participants’ postpartum glucose metabolism and could not assess GD resolution, nor postpartum insulin resistance and/or hyperglycemia." (PMID 39666338, 2024). "Hyperglycemia is a common event and is manageable even without insulin treatment." (PMID 38532073, 2024). "The possible causal pathways linking maternal visceral fat accumulation to increased birth weight are not fully elucidated, but insulin resistance and hyperglycemia could be partly responsible." (PMID 38184682, 2024). "However, a large-scale RCT the noted the use of intraoperative insulin does not reduce neurobehavioral deficits, and found that aggressive control of hyperglycemia will not improve neurocognitive outcome." (PMID 38902462, 2024). "Our previous study revealed that, after 4 weeks of hyperglycemic stress, insulin treatment was effective in controlling hyperglycemia, but was no longer able to prevent or reverse cardiac diastolic dysfunction, indicating that hyperglycemic memory was established 4 weeks after hyperglycemic stress." (PMID 39539089, 2024). "Insulinemia exhibits the highest values in the under-average group and the lowest in the stress hyperglycemia group, suggesting that low insulin secretion may explain high blood sugar levels in the acute stress hyperglycemia ratio group rather than IR." (PMID 39100008, 2024). "In the absence of insulin, glucose accumulates in the bloodstream, leading to hyperglycemia." (PMID 38606021, 2024). "Mismatching insulin administration to carbohydrate intake may explain these heterogeneous results, since this may lead to hypo- as well as hyperglycaemia regardless of changes in carbohydrate intake." (PMID 38967668, 2024). "When IR occurs in the liver, the tyrosine phosphorylation of IRS1 is severely damaged by hyperglycemia, leading to a decrease in the liver’s ability to absorb glucose, affecting proximal defects in the INSR, IRS1, PI3K, and AKT pathways and impairing the insulin transduction pathway." (PMID 39272556, 2024). "We demonstrated that in contrast to ubiquitous Glis3KO mice, pancreatic insulin expression and non-fasting blood glucose levels were not changed in Glis3-Pax8Cre mice confirming that these mice did not develop hypoinsulinemia/hyperglycemia." (PMID 38281222, 2024). "Therefore, the current results suggest that CC and/or metformin may also contribute to a reduction in hyperglycaemia by regulating gluconeogenic PEPCK enzyme levels in the ZDF rats, with insulin signalling playing a role in this process." (PMID 39339687, 2024). "In addition to reducing and suspending insulin delivery for hypoglycemia, the CIQ algorithm adjusts basal insulin delivery by a multiplier and delivers automated correction boluses for predicted or actual hyperglycemia." (PMID 38361690, 2024).
Hyperglycemia (continued). "Over the past few years of the COVID-19 pandemic, an increasing body of evidence suggests that insulin and other medications currently used in clinical practice for hyperglycemia control may not be safe for treating these patients." (PMID 39654800, 2024). "Intensive insulin therapy has evolved from multiple daily injections (MDI) to more advanced technological improvements that have been shown to decrease the chances of hypoglycemia and hyperglycemia, lessen fluctuations in blood sugar levels, and enhance the quality of life for patients." (PMID 39065641, 2024). "While a previous study suggested that metformin alone could control glucose concentrations as effectively as insulin in the burns setting, in our institution insulin was not infrequently employed to counteract stress hyperglycaemia." (PMID 38791089, 2024). "Endothelial cells are especially vulnerable to hyperglycemia because they express glucose transporters constitutively and at high levels (GLUT1), unlike other tissues such as skeletal muscle and adipose, both of which need insulin to induce the expression of glucose transporters (GLUT4)." (PMID 39584020, 2024). "A lack of GLP-1 could decrease β-cell mass and attenuate insulin secretion, with hyperglycemia as the overall outcome." (PMID 39205219, 2024). "Many authors propose a GIP-stimulated glucagon secretion even during hyperglycemia, but this hypothesis is controversial since in Type 1 diabetes patients without insulin secretion, GIP infusion cannot stimulate glucagon secretion during hyperglycemia." (PMID 37635984, 2023). "This suggests that this transient hyperglycemia is not primarily driven by reduced insulin release." (PMID 36834669, 2023). "Similar to type 1 diabetes models, Db/Db mice also exhibited a reduction in conventional lung DC but not CD64+ DC and lower frequency of Ki-67+ cells, suggesting that it is not the absence of insulin, but rather hyperglycaemia, that probably drives lung DC aberrations." (PMID 38093014, 2023). "Similarly, CVII is a commonly used route of administration for controlling PN-associated hyperglycemia; the insulin can be rapidly absorbed and can rapidly correct hyperglycemia, making CVII the preferred insulin infusion method for critically ill or hemodynamically unstable patients." (PMID 37674887, 2023). "Moreover, we included in the study the patients with HbAc1 < 6.9% who were not treated with insulin to exclude the direct effect of hyperglycemia and insulin therapy on adropin levels." (PMID 36830993, 2023). "We previously developed a mouse model with the R138X human LoF variant expressed from the endogenous locus (“knock-in”) and demonstrated that Zn-depleted islets with no detectable ZnT8 protein are still capable of secreting insulin in response to hyperglycaemia." (PMID 37396167, 2023). "However, in clinical trials treatment of elevated glucose levels with insulin did not improve stroke outcome, suggesting that collateral effects rather than hyperglycaemia itself aggravate ischemic brain damage." (PMID 37438755, 2023). "Collectively, the data establish that the disruption in PIMT’s activity (either expression or phosphorylation) attenuates gluconeogenesis and ameliorates hyperglycemia by improving hepatic insulin sensitivity and suppressing glucose biosynthesis from non-carbohydrate sources." (PMID 36866247, 2023). "Thus, the addition of Lixisenatide to insulin glargine improved overall and post-prandial hyperglycemia and is worth considering as an alternative to prandial insulin for patients who do not achieve HbA1c goals with newly initiated basal insulin." (PMID 37445623, 2023). "Non-life-threatening hyperglycemia requiring insulin infusion was found only in the AI group." (PMID 36676776, 2023). "Patients with hyperglycemia regardless of hemodialysis were prescribed increased OAD or insulin." (PMID 37089609, 2023).
Hyperglycemia (continued). "Thus, in insulin-treated patients, both icodec and BIF were given a loading dose, based on the results of the Phase 1 study, to reach homeostasis concentrations more quickly and minimize transient hyperglycemia." (PMID 38206709, 2023). "Insulin treatment prevented the upregulation in tubular damage markers Kim-1 and Ngal thus confirming that STZ does not exert tubular damage at the doses used in this study and that the observed effects might be attributed to hyperglycemia." (PMID 38069331, 2023). "Vglycin peptide exhibited beneficial effects on hyperglycemia by facilitating glucose metabolism and enhancing insulin sensitivity, but it could not increase insulin secretion." (PMID 36904097, 2023). "Some authors propose that loss of beta cell GIPR function due to cell stress in T2DM patients may reduce the inhibitory effect of insulin on glucagon secretion, leading to elevated GIP-stimulated glucagon secretion even during hyperglycemia, but this hypothesis is controversial." (PMID 37635984, 2023). "Notably, the results were obtained without the occurrence of severe hypo- and hyperglycemia and without appreciable differences in the total daily bolus insulin dose possibly due to a more appropriate within-day distribution of mealtime doses." (PMID 36900956, 2023). "However, it is unknown whether glyphosate can induce hyperglycemia by interfering with GSK-3β and FOXO-1, proteins involved in the regulation of glucose metabolism and insulin signaling in hepatocytes." (PMID 38274944, 2023). "There are no standardised management guidelines for HTGP; however, based on available evidence, we propose an algorithm for the management of HTGP and advise against the use of insulin in absence of hyperglycaemia and recommend adapting individualized approaches for blood purification techniques." (PMID 37233662, 2023). "One study showed that hyperglycemia increased mitochondrial metabolism through the advanced glycation end products (AGE) pathway, protein kinase C (PKC) and other pathways, and the high level of ROS generated during this process induced pyroptosis in the insulin-secreting β cells." (PMID 37250902, 2023). "This suggests that patients with hyperglycemic DKA may have been continued on insulin infusions based on continued hyperglycemia as opposed to resolution of acidosis." (PMID 38165186, 2023). "However, in this study, neither fasting glucose nor insulin use: as measures of the degree of hyperglycaemia exposure, were significant effect modifiers." (PMID 37865701, 2023). "Patients with T2DM are not insulin-dependent, but they may require insulin therapy to manage hyperglycemia if it cannot be achieved via diet alone or with oral hypoglycemic medications." (PMID 37370932, 2023). "Furthermore, others suggest that low BAIBA during hyperglycemic infusion conditions was paralleled with lower insulin secretory function regardless of presence or absence of hyperglycemia and T2D." (PMID 37780967, 2023). "A recent preclinical study found that the KD or short-term fasting can be used to protect against acute hyperglycaemia secondary to olanzapine usage independent of whole-body insulin usage, with blood glucose increasing in the chow-fed group but not the KD-fed group." (PMID 37139329, 2023). "Third, endothelial dysfunction, including the lack of insulin in patients with hyperglycemia, leads to decreased peripheral glucose uptake and elevated circulating free fatty acids, which may impair endothelium-dependent vasodilation." (PMID 37190521, 2023). "The etiology and pathogenesis of diabetic neuropathy are not yet completely clarified, but hyperglycemia, disorders of lipid metabolism, and abnormalities in insulin signaling pathways are currently considered to be the initiating factors for a range of pathophysiological changes in DPN." (PMID 38264279, 2023).
Hyperglycemia (continued). "Despite this finding, the insulin response of the pancreas may not be fully preserved in the ERαΔEC mice because they display relative fasting hyperglycemia that is not compensated by an increase in insulin secretion." (PMID 37591837, 2023). "In addition, AChE inhibition also increases the accumulation of acetylcholine, which can reduce insulin secretion; thus, insulin is not adequate to stimulate the uptake of adequate glucose in adipose and muscle tissues, leading to hyperglycemia and DM." (PMID 37755752, 2023). "We hypothesize that insulin monotherapy and combination therapy may have glycemic control effects, as demonstrated by the reduced deaths of mice due to hyperglycemia, although there was no significant improvement in blood glucose values in these two groups." (PMID 36756089, 2023). "Treatment of diabetic rats with INI moderately reduced hyperglycemia without causing hypoglycemic episodes, attenuated hyperphagia, and in the case of T2DM and diet-induced MS, INI increased tissue sensitivity to insulin and leptin and normalized glucose tolerance." (PMID 36834685, 2023). "However, this is not true in all cases, and hyperglycaemia can persist up to 2 years after discontinuation, suggesting long-lasting detrimental effects on insulin sensitivity and β-cell dysfunction or unmasking pre-existing glucose metabolism disorder." (PMID 37253115, 2023). "Additionally, O304 preserved β-cell function in an insulin resistant, hyperglycemic context in vivo and prevented, and reverted, the negative effects of chronic hyperglycemia on β-cell function/GSIS in vitro, at least in part by antagonizing mTORC1 signalling." (PMID 37626210, 2023). "In addition, lifestyle factors such as snacking and physical inactivity served as the major drivers of postprandial hyperglycemia independent of insulin-related indices." (PMID 37367911, 2023). "Following DSS exposure, wild-type BALB/c and C57BL/6 mice display increased levels of circulating RELMα, whereas RELMα-deficient mice are distinctly protected from DSS-induced colitis and glucose injection-induced hyperglycemia independent of changes in insulin levels." (PMID 36691020, 2023). "Biphasic soluble and isophane recombinant human insulin, or biphasic soluble and protamine insulin lispro had been tried without improvement, while inpatient evaluation revealed hyperglycaemia refractory to intravenous insulin at up to 6 units/hour while fasting." (PMID 37562398, 2023). "STZ administration is well described, reproducible model of type 1 diabetes, manifested by insulitis, reduction in insulin secretion capacity, and hyperglycemia, although due to its development in the absence of T- and B cell-contribution not perfectly resembles autoimmune human condition." (PMID 37851320, 2023). "Furthermore, during oGTT, we found that aging was associated with hyperinsulinemia in female mice, which was not triggered by hyperglycemia or enhanced insulin secretion, but rather by decreased insulin clearance." (PMID 37059838, 2023). "In summary, it is tempting to speculate that glomerulomegaly in T2DM is not due to hyperglycemia but to increased insulin levels." (PMID 37959313, 2023). "In this regard, D. officinale has been demonstrated to exhibit promising anti-hyperglycemia activity, such as not significantly reducing blood glucose and insulin levels in normal mice while increasing serum insulin levels and reducing serum glucagon levels in streptozotocin-induced diabetic rats." (PMID 37361228, 2023). "Insulin activates lipoprotein lipase and was successfully used in patients with increased glucose levels or even overt diabetic ketoacidosis, but also in patients without hyperglycemia." (PMID 35492338, 2022). "Additionally, IRE1α deletion in β-cells results in hypoinsulinemia and hyperglycemia due to a decrease in insulin production and secretion, probably from a lack of functional XBP1s." (PMID 35563231, 2022).
Hyperglycemia (continued). "The exact mechanisms of the onset of PDN are still not clear, and factors such as hyperglycemia, hyperlipidemia, microvascular changes of the blood supply to peripheral nerves as well as impaired insulin signaling could contribute to peripheral nerve damage." (PMID 35419564, 2022). "Hyperglycemia, which may result from the absence of insulin (DM-type 1) or due to a low response to insulin (DM-type 2), is one of the world’s emerging problems." (PMID 35684166, 2022). "This evidence suggests that the neuroprotective role of insulin can be independent of effects on hyperglycemia and local manipulation of insulin signaling may offer novel therapeutic peripheral nerve repair." (PMID 36277683, 2022). "Stress hyperglycemia seemed therefore not so deleterious if controllable by insulin." (PMID 35578303, 2022). "In this context, the evidence of the benefit of insulin therapy for hyperglycemia is lacking." (PMID 36542240, 2022). "In addition standardised fasting glucose is completed at gestational weeks 32 or 38 to capture additional participants who have fasting hyperglycaemia but have not had insulin introduced during the clinical trial." (PMID 36131291, 2022). "While closed-loop systems will correct some post-prandial hyperglycemia, this will not be as effective as accurate carbohydrate counting due to delays in subcutaneous insulin absorption, and closed-loop systems are not able to mitigate excessive boluses delivered for overestimated carbohydrates." (PMID 32914648, 2022). "Second, the TyG index measured during the acute phase of stroke might not precisely reflect the patient’s insulin sensitivity, given that acute stroke could lead to stress hyperglycemia." (PMID 36451149, 2022). "Co-transfection of a synthetic expression unit harboring the transgene (i.e., insulin and GLP1) under the control of a synthetic promoter including binding sites for endogenous transcription factors (i.e., NFAT) allows for expression of the desired therapeutic protein in response to hyperglycemia." (PMID 34586617, 2022). "In 174 patients with CS (pituitary in 106, ectopic in 25, adrenal in 43), baseline median HbA1c was 6.9% (range, 4.9-13.1), with 41 (24%) patients not on any therapy for hyperglycemia, 93 (52%) on oral medications, and 64 (37%) on insulin (median daily units of 58; range, 10-360)." (PMID 34988348, 2022). "Therefore, it is necessary to regularly use insulin to prevent and treat “hospital-related hyperglycemia” in non-diabetic patients who need surgery." (PMID 35237639, 2022). "By contrast, another study has demonstrated that activation of VMHSF1 neurons with designer receptors exclusively activated by designer drugs (DREADD) does not induce significant hyperglycemia, but a lower blood glucose in the context of both glucose tolerance and insulin tolerance tests." (PMID 35619170, 2022). "In contrast, when a GCK‐MODY affected pregnant woman carries a GCK‐MODY affected fetus, the fetal insulin secretion and hence, fetal growth will be normal if the maternal hyperglycemia is not treated since the fetus has the same elevated glucose set‐point as the mother." (PMID 36483860, 2022). "Insulin treatment has been used for almost four decades in GDM pregnancies in which lifestyle and diet interventions fail and has shown improvement regarding macrosomia rates and adverse pregnancy outcomes by increasing maternal insulin and decreasing maternal hyperglycaemia." (PMID 35258482, 2022). "This hyperglycemia is the result of several processes that mainly include an absence of gluconeogenesis inhibition and the presence of insulin resistance (perhaps as a consequence of high growth hormone, cortisol and catecholamine release, or defective proinsulin processing and secretion)." (PMID 36139921, 2022).